GRHL1 (grainyhead like transcription factor 1)
Description:
Transcription factor involved in epithelial development. Binds directly to the consensus DNA sequence 5'-AACCGGTT-3'. Important regulator of DSG1 in the context of hair anchorage and epidermal differentiation, participates in the maintenance of the skin barrier. There is no genetic interaction with GRHL3, nor functional cooperativity due to diverse target gene selectivity during epithelia development (By similarity). May play a role in regulating glucose homeostasis and insulin signaling. [Isoform 1]: Functions as a transcription activator. [Isoform 2]: May function as a repressor in tissues where both isoform 1 and isoform 2 are expressed.
Synonyms: LBP32; MGR; TFCP2L2; LBP-32; NH32
Tractability: No criterion of Open Targets' tractability assessment is met for any kind of drug.
Gene: Protein-coding gene on chromosome 2 (9,951,693 to 10,002,277, forward strand). Ensembl gene ENSG00000134317.
Subcellular location: Nucleus
Subcellular location (Human Protein Atlas): Nucleoplasm; Vesicles
Pathways (Reactome):
Metabolism: PPARA activates gene expression
Gene Ontology:
Molecular function: chromatin DNA binding; DNA binding; DNA-binding transcription activator activity, RNA polymerase II-specific; DNA-binding transcription factor activity; DNA-binding transcription factor binding; identical protein binding; protein binding; protein homodimerization activity; RNA polymerase II cis-regulatory region sequence-specific DNA binding; sequence-specific DNA binding; sequence-specific double-stranded DNA binding; transcription cis-regulatory region binding; DNA-binding transcription factor activity, RNA polymerase II-specific
Biological process: positive regulation of transcription by RNA polymerase II; regulation of DNA-templated transcription; epidermis development; regulation of transcription by RNA polymerase II
Cellular component: nucleoplasm; nucleus; chromatin
Genetic constraint (gnomAD): Loss-of-function variants: 17 observed, 30.56 expected, observed/expected ratio (o/e) 0.56, 90% interval 0.38 to 0.83. The upper end of that interval is the gene's LOEUF score, 0.83, which puts it in group 3 of 6, group 1 being the genes least tolerant of losing a copy. Missense variants: 328 observed, 454.86 expected, observed/expected ratio (o/e) 0.72, 90% interval 0.66 to 0.79. Synonymous variants: 157 observed, 172.8 expected, observed/expected ratio (o/e) 0.91, 90% interval 0.8 to 1.04.
Homologues: Orthologues: macaque GRHL1 (99% identical), dog GRHL1 (97% identical), chimpanzee GRHL1 (96% identical), mouse Grhl1 (95% identical), rat Grhl1 (94% identical), pig GRHL1 (94% identical), guinea pig GRHL1 (91% identical), rabbit GRHL1 (84% identical), tropical clawed frog grhl1 (80% identical), zebrafish grhl1 (70% identical), Caenorhabditis elegans grh-1 (29% identical), Drosophila melanogaster gem (17% identical). Paralogues in human: GRHL2 (57% identical), GRHL3 (46% identical), TFCP2 (21% identical), UBP1 (20% identical), TFCP2L1 (19% identical).
Diseases named in the same sentence as GRHL1 in open-access papers:
GRHL1 is named in the same sentence as 28 diseases in open-access papers, as found by Europe PMC text mining. Sharing a sentence is not in itself a finding about the gene and the disease. The quoted sentences say what the papers report.
neuroblastoma (7 papers, 2015 to 2022). Neuroblastoma (NB) is the most common solid, extracranial childhood tumor. "In brain cancer, particularly primary neuroblastoma, an early childhood neuroendocrine tumour originating from neural crest cells, GRHL1 functions as a tumour suppressor and its upregulation correlates with a favourable patient prognosis." (PMID 35269877, 2022). "In cases of high GRHL1 expression, in neuroblastoma, tumor progression was suppressed, as well as patient survival was more favorable." (PMID 34842635, 2021). "GRHL1 was reported to involve in the occurrence and development of skin squamous cell carcinoma and neuroblastoma." (PMID 33931584, 2021). "In neuroblastoma, patients with high levels of GRHL1 expression show favorable prognosis, consistent with the suppressed tumor growth phenotype seen in the xenografts carrying forced GRHL1 expression in MYCN-amplified neuroblastoma cells." (PMID 32974388, 2020). "We showed that HDAC2 cooperates with MYCN to suppress apoptosis mediated by miR-183, and that HDAC3 interacts with MYCN to transcriptionally repress the GRHL1 transcription factor, which exerts tumor suppressive effects in neuroblastoma." (PMID 27572323, 2016). "High-level GRHL1 expression favorably influences neuroblastoma biology at the molecular and phenotypic levels." (PMID 27572323, 2016). "Lastly, GRHL1 appears to have a more minor role in tumorigenesis, nonetheless it is implicated as a tumour suppressor gene in neuroblastoma and oesophageal cancer and loss of Grhl1 predisposes animals to tumour development in a skin cancer model." (PMID 35269877, 2022). "Genome-wide analysis of neuroblastoma cells identified 170 genes as potential GRHL1 targets; most of them are involved in nervous system development, cell adhesion, anchorage-independent growth, proliferation, differentiation, neuroblastoma genesis and spreading." (PMID 35269877, 2022). "We can assume that the oncogenic effects of PAX5 may be associated with its negative regulation of expression of GRHL1 and GRHL3, since GRHL1 has been shown to be a tumor suppressor in neuroblastoma, whereas GRHL3 is a tumor suppressor in head and neck SCC." (PMID 34570823, 2021). "We conclude that GRHL1 activates CD9 transcription in neuroblastoma cells." (PMID 27572323, 2016). "Having shown that CD9 is downstream of GRHL1 in neuroblastoma cells, we assessed whether CD9 is differentially expressed in primary tumors." (PMID 27572323, 2016). "At the same time another gene the Grainyhead-like 1 (GRHL1), which is known to be critical in Drosophila neural development, was found to be one of the main targets of HDAC inhibitor treatment in neuroblastoma." (PMID 34842635, 2021). "Here we identified GRHL1 as a transcriptional activator of the CD9 gene and showed that MYCN and HDAC5 transcriptionally repress CD9 in neuroblastoma." (PMID 27572323, 2016). "Thus, it appeared that neuroblastoma with or without MYCN amplification, manifested low proliferation rates and sensitivity to therapy if GRHL1 was present." (PMID 34842635, 2021).
breast carcinoma (4 papers, 2016 to 2025). "GRHL1, a key transcription factor involved in epithelial cell differentiation and maintenance, play a role in breast cancer progression by influencing epithelial-mesenchymal transition (EMT) and cell proliferation." (PMID 40969325, 2025). "A further exploration of genes enriched in cancer cells relative to normal cells using Kaplan–Meier Plotter revealed that breast cancer patients with elevated expression of GRHL1, TRPS1, and ZHF217 have a decreased rate of survival relative to patients with low expression of these genes." (PMID 37627195, 2023). "Three transcription factors, GRHL1, VGLL1, and ELF5 are strong candidates for the cell autonomous regulation of ST14/Prss14 in basal type ER− breast cancer patients and ER+ luminal A type breast cancer cell lines." (PMID 27167193, 2016).
skin cancer (4 papers, 2014 to 2024). "Here we present data concerning the role of GRHL1 transcription factor in development of skin cancers." (PMID 24586629, 2014). "In this article we would like to present results concerning the role of GRHL1 transcription factor in maintenance of the epidermis, in the immunology of the skin, and in skin cancer development." (PMID 24586629, 2014). "Both VDR and GRHL1 have been studied in the context of skin cancers." (PMID 39063155, 2024). "It is thus likely that, in the context of human NMSC, the expression of both GRHL1 and GRHL3 must be simultaneously reduced to delay epidermal cells differentiation and/or induce tumor promoting inflammatory microenvironment in the skin, which would enable skin tumor progression." (PMID 29301499, 2018).
squamous cell carcinoma (4 papers, 2018 to 2024). A carcinoma arising from squamous epithelial cells. "Also, our results indicated that the Grhl1-null mice display increased susceptibility to chemically-induced skin tumorigenesis and deletion of Grhl3 in the epidermis increases the occurrence of squamous cell carcinoma (SCC) of the skin." (PMID 34570823, 2021). "Grhl1-null mice exposed to chemically induced skin carcinogenesis develop more squamous cell carcinomas with an earlier onset than their control wild-type littermates." (PMID 39063155, 2024). "When subjected to the standard chemical skin carcinogenesis protocol, the Grhl1-null mice develop more squamous cell carcinomas (SCC), with an earlier onset, than their control wildtype littermates." (PMID 29301499, 2018). "Expression levels of two of the examined genes – GRHL1 and GRHL3 – were significantly reduced in basal cell carcinoma (BCC) samples as well as in squamous cell carcinoma (SCC) samples, in comparison with the control healthy tissue from the same patient." (PMID 29301499, 2018).
benign papilloma (2 papers, 2014 to 2020). "In the light of these results we can state that loss of Grhl1 supports the progression of papillomas to carcinomas in a mouse model." (PMID 24586629, 2014). "This affected 32 papillomas (34%) in Grhl1+/+ mice and 4 papillomas (8%) in Grhl1−/− mice." (PMID 24586629, 2014). "In total the Grhl1−/− mice developed 49 papillomas, Grhl1+/+ –94 papillomas (p = 0.022)." (PMID 24586629, 2014). "There may exist as yet unidentified additional target genes of GRHL1 regulation whose expression is dysregulated in the Grhl1-null mice, and this dysregulation may play a part in the decrease in papilloma incidence and increased conversion rate of papillomas to SCC." (PMID 24586629, 2014). "We did not observe significant differences between Grhl1+/+ and Grhl1−/− mice in the onset of development of papillomas." (PMID 24586629, 2014).
colon cancer (2 papers, 2020 to 2021). "In colon cancer, GRHL1 expression was higher in tumor tissues than normal colon tissues and the low levels of GRHL1 correlated with better overall survival of cancer patients." (PMID 33931584, 2021). "In accordance with this, knockdown of GRHL1 inhibited the proliferation of human colon cancer cells." (PMID 33931584, 2021). "But in colon cancer, GRHL1 promoted the proliferation of colon cancer." (PMID 33931584, 2021).
lung carcinoma (2 papers, 2021 to 2023). "Thus, our findings first demonstrated the function of GRHL1 in NSCLC and elucidated the molecular mechanisms for GRHL1 functioning as an oncogenic gene in NSCLC which provided a new therapeutic strategy for targeting GRHL1 to cure lung cancer." (PMID 33931584, 2021). "In lung cancer, however, the function of GRHL1 has not been studied." (PMID 33931584, 2021).
non-melanoma skin carcinoma (2 papers, 2018 to 2024). "GRHL1 acts as a tumor suppressor in non-melanoma skin cancer (NMSC)." (PMID 39063155, 2024). "To test this hypothesis we assayed the expression of all the GRHL1–3 genes in two subtypes of human non-melanoma skin cancer samples – BCCs and SCCs." (PMID 29301499, 2018).
non-small cell lung carcinoma (2 papers, 2021 to 2022). A group of at least three distinct histological types of lung cancer, including non-small cell squamous cell carcinoma, adenocarcinoma, and large cell carcinoma. "In the context of lung cancer, a recent study identified upregulation of GRHL1 in non-small cell lung cancer (NSCLC) that correlates with poor patient survival." (PMID 35269877, 2022). "In this study, we found that GRHL1 was upregulated in non-small cell lung cancer (NSCLC) and correlated with poor survival of patients." (PMID 33931584, 2021).
type 2 diabetes (2 papers, 2019 to 2022). "Fasting blood glucose levels, including in individuals with type 2 diabetes, are negatively correlated with GRHL1 expression." (PMID 35013237, 2022). "In addition, human GRHL1 expression negatively correlates with fasting blood glucose levels, notably also including in individuals with type 2 diabetes." (PMID 35013237, 2022). "Human skeletal muscle GRHL1 expression negatively correlates with fasting blood glucose not only when considering every participant of the cohort, but even more evidently so in individuals with impaired glucose tolerance (IGT), or type 2 diabetes (T2D)." (PMID 35013237, 2022).
corneal dystrophies (1 paper, 2023). "Missense variants in heterozygosis were found in both GRHL1 (p.(Val287Gly)) and SLC4A4 (p.(Gly50Ala)), causally related to corneal dystrophies." (PMID 37895187, 2023).
hepatocellular carcinoma (1 paper, 2022). A malignant tumor that arises from hepatocytes. "Of the GRHL1-3 factors, GRHL2 acts as an oncogene in hepatocellular carcinoma (HCC) and HCC cells show decreased proliferation following GRHL2 downregulation." (PMID 35269877, 2022).
melanoma (1 paper, 2024). A malignant, usually aggressive tumor composed of atypical, neoplastic melanocytes. "In vitro experiments showed that melanoma-conditioned media induce upregulation of the transcriptional repressor Slug in keratinocytes and consequently decreased the expression of the transcription factor Grainyhead like 1 (Grhl1), a transcriptional activator of Dsg1." (PMID 39201498, 2024). "The involvement of keratinocyte Slug/Grhl1/Dsg1 pathway activation in melanoma cell movement is supported by patients’ samples analysis where keratinocyte Dsg1 and Slug were found negatively and positively correlated, respectively, to the extent of intraepidermal melanoma spread." (PMID 39201498, 2024).
Palmoplantar keratoderma (1 paper, 2021). Abnormal thickening of the skin of the palms of the hands and the soles of the feet. "Grhl1 knockout mice exhibit palmoplantar keratoderma, impaired hair anchoring, and desmosomal abnormalities." (PMID 34244796, 2021).
tumor (16 papers, 2014 to 2025). "Likewise, overexpression of transcription factor GRHL1 and metabolic enzyme glutaminase, both found to be identified by IHC analyses, were significantly higher in EC tissues than normal endometrium, associating these proteins with tumour proliferation and metabolic remodelling." (PMID 41312167, 2025). "Overexpression of GRHL1 and glutaminase correlated with tumour proliferation and metabolic remodelling." (PMID 41312167, 2025). "The authors showed that GRHL1 binds to the promoters of cell cycle-related genes CDC27, RAD21, CDC7, and ANAPC13 to induce their transcription, while GRHL1 knockdown inhibits NSCLC tumour growth." (PMID 35269877, 2022). "The results showed that the mRNA level of GRHL1 is significantly higher in tumor tissues than in normal tissues." (PMID 33931584, 2021). "The results showed that 96% of tumor tissues expressed significantly higher levels of GRHL1 than the adjacent normal tissues and this was further validated by quantification of the staining." (PMID 33931584, 2021). "To assess the effect of GRHL1 on tumor growth in vivo, we generated an A549 stable cell line with GRHL1 knockdown." (PMID 33931584, 2021). "The results demonstrated that the expression of GRHL1 was higher in most tumor tissues than that in normal lung tissues." (PMID 33931584, 2021). "GRHL2 usually acted as a tumor suppressor due to inhibiting migration and invasion in several types of cancer; also, GRHL1 suppresses SCC." (PMID 34888136, 2021). "GRHL2, whose binding motif is similar to that of GRHL1, functioned as a tumour suppressor, and its expression reduces invasion and migration in GC50." (PMID 28801683, 2017). "In-depth transcriptome analyses and ChIP-qPCR identified the cell surface glycoprotein, CD9, as a major downstream player and direct target of the recently described GRHL1 tumor suppressor." (PMID 27572323, 2016). "Compared to adjacent normal tissues, tumor tissues exhibited significantly reduced expression of PTGIS, DGKB, HSD17B13, INMT, and ACACB, while PLA2G10, GRHL1, LIPG, and PLA2G4F were markedly upregulated." (PMID 40426878, 2025). "We performed immunohistochemical (IHC) analysis within tumor heterotransplants derived from UROtsa As_I cells to get a better understanding of protein localization in vivo for SOX2, IVL, and GRHL1." (PMID 37298099, 2023). "To further investigate the expression of GRHL1 in NSCLC, we examined GRHL1 protein expression in tumor and adjacent normal tissues from 19 NSCLC patients." (PMID 33931584, 2021). "We discovered that the expression of two genes – GRHL1 and GRHL3 – is reduced in a coordinated manner in tumor samples, in comparison to the control healthy skin samples obtained from the same individuals." (PMID 29301499, 2018). "GRHL1, a transcription factor with tumor-suppressive behavior in epithelial cancers, showed negative SHAP contributions suggestive of a protective, control-associated signature." (PMID 40941703, 2025). "It has been previously demonstrated that the TP63/TP53L, ERG, GRHL1/Get-, HNF1A/TCF-1, SPI1/PU.1, WT1 and GLIS2, FOXM1 and FOXP3 transcription factor networks, which are mediated by HNF4A, can regulate the expression of Trop2 in tumor tissues." (PMID 25779928, 2015). "Therefore we applied the standard two-stage skin carcinogenesis protocol in Grhl1−/− and Grhl1+/+ mice, using DMBA and TPA as tumor inducer and promoter, respectively." (PMID 24586629, 2014).
cancer (8 papers, 2014 to 2024). A tumor composed of atypical neoplastic, often pleomorphic cells that invade other tissues. "GRHL1-3 and their transcriptional targets have been shown to drive comparable cellular processes in Drosophila, C. elegans, zebrafish and mice, and have recently also been implicated in the aetiology and/or progression of a number of human congenital disorders and cancers of epithelial origin." (PMID 35269877, 2022). "Research in esophageal squamous cell carcinoma found that GRHL1 was down-regulated in cancer cells and cancer tissues and correlated with a reduced overall survival rate." (PMID 33931584, 2021). "The study of GRHL1 has focused on embryonic development and there are few studies of GRHL1 in cancer research." (PMID 33931584, 2021). "This indicated that the functions of GRHL1 were different depending on the types of cancer." (PMID 33931584, 2021). "Statistical analysis of the quantified staining results from cancer tissues divided the cancer samples into two groups depending upon the median of GRHL1 expression level (median:11936.5, analyzed by GenePix; high expression: n = 47, the low expression: n = 47)." (PMID 33931584, 2021). "Overexpressing GRHL1 inhibited the invasion of cancer cells." (PMID 33931584, 2021). "The role of GRHL1 and its target genes in breast development and cancer is still unknown." (PMID 35269877, 2022). "The role of GRHL1 and its target genes in head and neck development and cancer is still unknown." (PMID 35269877, 2022). "However, little is known about the biological functions of GRHL1 in cancer." (PMID 33931584, 2021). "Here we demonstrate that, even though GRHL1 and GRHL3 share a high degree of sequence homology, have almost identical target DNA binding sites and display very similar expression patterns in the epidermis, the molecular mechanisms linking them to cancer are very different." (PMID 24586629, 2014).
genetic disease (1 paper, 2023). "Additionally, several studies implicate a functional role for the GRHL1 protein in cancer, further underscoring its potential role in genetic disease." (PMID 38049725, 2023). "However, it is crucial to identify all potential binding sites throughout the genome to fully understand the underlying molecular basis of transcriptional regulation, regulatory networks, genomic traits, and genetic disease mediated by GRHL1." (PMID 38049725, 2023).
GRHL1 also shares sentences with these, for which no sentence is quoted: atherosclerosis (1 paper); bacterial infections (1); basal cell carcinoma (1); cardiovascular diseases (1); fetal growth restriction (1); Impaired glucose tolerance (1); keratoconus (1); oesophageal cancer (1); prostate carcinoma (1); skin squamous cell carcinoma (1); type 1 diabetes (1).